ISG15 (ISG15 ubiquitin like modifier)
Diseases named in the same sentence as ISG15 in open-access papers (continued):
Sharing a sentence is not in itself a finding about the gene and the disease.
viral infection (continued). "For example, mammalian cells have several ways to shut down host and virus translation during viral infection: the IFIT family of proteins, ISG15, and ZAP are all examples of proteins that are induced by interferon and prevent viruses and hosts from translating RNA." (PMID 33902453, 2021). "Unlike humans, in whom loss of ISG15's role in controlling IFN signaling does not present with unusually severe viral infection, mice are more susceptible to viral infection." (PMID 34258050, 2021). "Thus, our unique Virotrap method revealed a functional link between ISG15 and RNF213, as well as an undiscovered role for RNF213 in host defense pathways to both bacterial and viral infections." (PMID 34599178, 2021). "Interestingly, MSC are usually resistant to viral infection due to their expression of ISGs such as IFITM, IFI6, ISG15, SAT1, PMAIP1, p21/CDKN1A, and CCL2 that preempt viral infection." (PMID 33808241, 2021). "In order to determine whether reduced affinity of Lpro for ISG15 affects the production of IFN and ISGs, expression of specific mRNAs was analyzed by reverse transcription-quantitative PCR (qRT-PCR) during viral infection." (PMID 32295921, 2020). "Recombinant ISG15 added to cells exhibited cytokine-like activity that stimulated PAMs to assume an anti-viral state that enabled them to inhibit PRRSV replication and resist viral infection." (PMID 32927637, 2020). "In conclusion, using proteomic analysis we found that the DEPs SPP1, IFIT5, ISG15, VCL, and SDC1 are significantly changed in PSV-infected PK-15 cells, suggesting that these proteins may be closely related to viral infection." (PMID 32575635, 2020). "As the major ISG15 de-conjugating enzyme, USP18 is an off-switch in ISGylation, striping ISG15 from its target proteins (known as deISGylation) and playing important role in viral infections through its ISG15 protease activity." (PMID 32248821, 2020). "ISG15 is one of the most abundantly induced ISGs and plays an important role in viral infection, but its role in regulating CSFV replication has not been extensively explored." (PMID 32093773, 2020). "Classical ISGs responsible for inhibition of viral infection include OAS1, MX1, and ISG15." (PMID 32760370, 2020). "Meanwhile, we found that IFNs could significantly trigger the production of a variety of IFN-induced genes (IFIT1, IFITM3, Mx-1, OASL, ISG15, PKR, GBP1, Viperin, BST2, IRF-1, and CXCL10) and MHC molecules, which play key roles in resistance to virus infection." (PMID 32655518, 2020). "Notably, following viral infection, the levels of these transcripts (with the exception of EGR1) decreased at 1 dpi, with the levels of IFIT3 and ISG15 remaining significantly depleted at 3 dpi." (PMID 31451757, 2019). "Moreover, ISG15, STAT1, IRF7 and DDX58 were identified as the hub genes that play a pivotal role in response to viral infection and their expression were up-regulated with ageing." (PMID 30641486, 2019). "Regarding upregulated DEGs, a clear relationship with the innate immune response against viral infection was observed, being unigenes detected those coding pattern recognition receptors (PRRs) (DHX58), and IFN-stimulated genes (ISG15, Mx, STAT1, HERC5, IFI44, IFIT-1, NUP133, and TRIM21)." (PMID 30065724, 2018). "Notably, UL26 itself is subject to ISG15 modification; however, many questions remain about how the interactions between UL26 and the ISG15-machinery contribute to viral infection." (PMID 30134546, 2018). "Moreover, the study of molecular effects of HPV transfection of trophoblast cells identified two candidate genes, ISG15 and IFIT1, possibly involved in the antiviral response after interferon induction upon viral infection." (PMID 28869524, 2017). "At 2 hours post-infection (hpi), respiratory levels were slightly reduced in ISG15-/- BMDM, but at later stages there was a similar decrease in the OCR (both basal and FCCP-induced) in both populations, indicating that viral infection reduces OXPHOS." (PMID 29077752, 2017).
viral infection (continued). "Three of the genes (ISG15, OASL, IL16) have previously been reported to be associated with host response to viral infection, although they are not entirely specific to such a response." (PMID 28588308, 2017). "The expression of ISG15, the enzymes responsible for its conjugation, and cellular target proteins such as DDX58, IRF3, PKR, and STAT1 are strongly induced by treatment of type I IFNs or viral infection." (PMID 27427993, 2016). "ISGylation is not induced because virus infection alone does not induce the synthesis of UbcH8, the E2 enzyme for ISGylation, and probably the other ISG15 conjugation enzymes." (PMID 27587337, 2016). "While secretion of ISG15 in granulocytes is shown to activate T cells and natural killer cells to produce IFNγ in mycobacterial infection, the role of secreted ISG15 in viral infection is not clear." (PMID 27564865, 2016). "This duration and dosage of IFN-β pretreatment was sufficient to induce free ISG15 but no detectable ISGylation at the time of virus infection." (PMID 27587337, 2016). "Here the authors demonstrate that, unlike in mice, human ISG15 stabilizes UPS18 and that ISG15-deficient human cells are more resistant to viral infection." (PMID 27193971, 2016). "The MX, TRIM22, ISG15, OAS, and SFTPA1, B gene are important effectors of innate immune response against viral infections." (PMID 25883591, 2015). "In order to exclude that ISG15 generally regulates macrophage apoptosis rather than controlling apoptosis induction upon viral infection, we again used the general apoptosis activators epopside and staurosporine." (PMID 24137104, 2013). "Remarkably, the role of ISG15 during CHIKV infection appears to be conjugation independent, suggesting a non-classical role for ISG15 during viral infection." (PMID 22028657, 2011). "The precise mechanism by which ISG15, independent of UbE1L mediated conjugation, contributes to the control of viral infection is currently unclear." (PMID 22028657, 2011). "These mice express free ISG15, but do not form ISG15 conjugates following LPS stimulation or during viral infection." (PMID 21994614, 2010). "ISG15-deficient humans suffer from type I interferonopathy and mycobacterial disease (due to loss of IFN-γ induction) but show no unusual susceptibility to viral infections." (PMID 41472304, 2025). "The interferon-stimulated genes (ISGs), ISG15 and MX Dynamin-Like GTPase 1 (MX1), were also elevated at 3 dpi, indicating that airway tissue explants are not only infectable but can also respond to viral infection by activating interferon-mediated host innate defense pathways." (PMID 40279421, 2025). "Thus, the strategy to knock out Egln1 in mice was reliable and successful, and the deletion of Egln1 exhibits no obvious effects on the expression of Ifn-β or Isg15 in the lung, spleen, and liver without virus infection." (PMID 38670937, 2024). "The authors of that article attributed the protective actions of ISG15 to the ISGylation of CVB3 2A protease, limiting CVB3-induced cleavage of host eukaryotic initiation factor 4γ (eIF4G) in cardiomyocytes, which ordinarily promotes viral infection by restricting host cell protein translation." (PMID 38665231, 2024). "Elsewhere, there has been renewed interest in the complex pathobiology of ISGs, and especially ISG15, since the emergence of SARS-CoV-2, and the recognition that ISG15 plays a key role in the defence against viral infection and in the immune response to viral infection." (PMID 38665231, 2024). "Various studies have demonstrated that ISG15, 2′-5′ oligoadenylate synthase (OAS2), double-stranded RNA protein kinase R (PKR), interferon-induced transmembrane protein 1 (IFITM1), and nitric oxide synthase (NOS) play a crucial role in inhibiting viral infections." (PMID 37256060, 2023).
viral infection (continued). "To test whether RUNX1 could directly regulate IFN-β signaling, we analyzed the expression of IFNB1, MxA and ISG15 in the A549 cells without viral infection." (PMID 35248104, 2022). "It is not only IRF7 that responds to viral infection, as this is also common to a group of interferon-stimulated genes (ISG), such as Orthomyxovirus resistance gene (Mx), oligoadenylate synthetase (OAS), ISG15, and Interferon-induced transmembrane protein 2 (IFITMs)." (PMID 36164603, 2022). "Double knockout (dKO) UbE1L–/– and ISG15–/– C57BL/6J mice with 6 and 9 days old infected with CHIKV exhibited increased levels of pro-inflammatory cytokines and chemokines, correlating to human cytokine and chemokine profile, and also showed increased lethality rate to viral infection." (PMID 34675908, 2021). "The functional significance of ISG15 as a potential target of SUMOylation during viral infection has not been explored further, but may warrant attention." (PMID 33806893, 2021). "Previous research showed that myxovirus (influenza virus) resistance 1 (MX1) and ISG15 were up-regulated in the PBMCs from PI cattle which infected with BVDV-1, suggesting that the CP and NCP BVDV could lead the production of ISGs to resist viral infection." (PMID 34872498, 2021). "Interestingly, MSC are usually resistant to viral infection due to their expression of interferon (IFN) stimulated genes (ISG) such as IFITM (interferon-induced transmembrane family), IFI6, ISG15, SAT1, PMAIP1, p21/CDKN1A, and CCL2 that preempt viral infection." (PMID 32766251, 2020). "Notably, we found IL1α (a cytokine) and ISG15 (an interferon-induced protein) were up-regulated in SARS-CoV-2-infected HPAEpiC cells, which indicated some innate immune pathways were activated following viral infection." (PMID 33293527, 2020). "This interesting observation implies that ISG15 secretion may not be an inevitable consequence of ISG15 upregulation after IFNs stimulation or virus infection, and it may require activation of additional cellular pathways." (PMID 32927637, 2020). "In order to figure out whether mRNAs and miRNAs in the ceRNA network have effects on viral infection, we investigated the effect of selected six representative mRNAs (CMPK2, ISG15, PARP10, SAMD9, GBP1, and RIG-I) involved in the ceRNA network upon HTNV infection." (PMID 32232013, 2020). "Despite the initial identification of ISG15 as an antiviral molecule, patients who lack Isg15 do not appear to be overly sensitive to viral infection, instead they have difficulty clearing bacterial infections or the BCG vaccine due to reduced interferon gamma immunity." (PMID 31772204, 2019). "Since the lack of ISG15 seems to cause alterations in OXPHOS, such increase in the sensitivity to viral infections in ISG15-/- and Ube1L-/- mice might be explained as a result of defects in RLR-mediated antiviral responses, supporting the role of ISG15 as a regulator of mitochondrial functions." (PMID 30428561, 2018). "When we treated cells with EGCG before HCV dsRNAs stimulation, the HCV dsRNAs-induced IFN-λ1, RIG-I, TLR3 and several antiviral ISGs (ISG15, MxA) expressions were significantly enhanced, indicating that EGCG might be used as an agent to enhance the innate immune responses during viral infections." (PMID 26879672, 2016). "Individuals lacking ISG15 exhibit elevated ISG expression, which may confer an enhanced protection against viral infection, but do not exhibit any of the side-effects associated with IFN treatment." (PMID 27193971, 2016). "Moreover, peritoneal macrophages from mice lacking ISG15 are neither able to phagocyte infected cells nor to block viral infection in co-culture experiments with VACV-infected murine embryonic fibroblast (MEFs)." (PMID 24137104, 2013).
viral infection (continued). "Moreover, we observed that IFNβ-induced the mRNA level of Isg15, Isg54, and Isg56 were enhanced in BMDMs and PMs from Lyz2-Cre;Sec10fl/fl mice compared with Sec10fl/fl mice, indicating that Sec10 can block the downstream signaling transduction of IFN triggered by the viral infection." (PMID 40920886, 2025). "Importantly, the feIFN-ω’ can effectively promote the expression of antiviral proteins IFIT3, ISG15, Mx1, and ISG56, and further enhance host defense to eliminate FPV infection in vivo, suggesting a potential candidate for the development of therapeutic agent against feline viral diseases." (PMID 35068319, 2022). "Because ROS production is tightly controlled by mitochondrial membrane potential, low levels of ROS in ISG15-/- BMDM might be the result of abnormalities in the transmembrane proton gradient due to the absence of ISG15, and could affect the immune response against viral infections." (PMID 30428561, 2018). "However, one puzzling problem was that ISG15 and Mx expression were down-regulated; this expression pattern might not benefit the anti-LCDV defense and was different from other host defenses against virus infections." (PMID 29304016, 2018). "Moreover, clear differences in viral-induced cell death were observed in these cells in the absence of ISG15, indicating that ISG15 could regulate macrophages programmed cell death in response to viral infection." (PMID 24137104, 2013). "However, a recent study of Chikungunya virus infection in a murine model showed that the antiviral effect of mouse ISG15 is independent on its ability to form conjugates with substrate proteins, which suggests a non-classical role for ISG15 during viral infection." (PMID 23028660, 2012). "In the absence of viral infection, STING knockout had certain downregulation on the mRNA level of Isg15." (PMID 41373601, 2025). "The gene expression of ISG15 and CXCL-10 was induced upon virus infection in both types of cells; however, it was not affected by Iristatin." (PMID 39821815, 2025). "It is interesting to note that PKR ISGylation at Lys-69 and Lys-159, both located in the ds-RNA binding motif, by ISG15 also triggers PKR and eIF-2α phosphorylation in the absence of viral infection." (PMID 33968942, 2021). "Unlike Ub, expression of ISG15 is IFN-induced and can be rapidly upregulated in response to viral infection." (PMID 30483224, 2018). "The data showed that neither ISG15 nor IFIT1 were upregulated in HPV-positive placenta samples, probably illustrating that HPV was not in its active phase of viral infection at the time when samples were collected from patients." (PMID 28869524, 2017). "ISG15 has not previously been identified as affected by MRV infections, but has been identified in numerous other viral infections." (PMID 23240068, 2012). "A four-gene blood signature that includes ISG15, IL16, 2′,5′-Oligoadenylate Synthetase Like (OASL), and Adhesion G protein-coupled Receptor E5 (ADGRE5) yielded an AUC of over 0.90 in distinguishing various viral infections from non-viral conditions." (PMID 39861921, 2025). "However, unlike Ub, ISG15 and the ISGylation machinery are robustly induced by type I IFN and can be upregulated upon viral infection." (PMID 32295921, 2020). "The data presented above suggest that the virus infection itself could be the signal that triggers apoptosis in macrophages, as the VACV cycle appears to be prematurely inhibited in the absence of ISG15 in these cells." (PMID 24137104, 2013).
COVID-19 (103 papers, 2020 to 2025). A disease caused by infection with severe acute respiratory syndrome coronavirus 2. "Notably, ISG15 deficiency is associated with severe mycobacterial infections, and increased ISGylation has been observed in peripheral blood mononuclear cells from Coronavirus Disease 2019 patients, highlighting a critical role for ISG15 in host defense." (PMID 40570956, 2025). "Although we showed a more rapid decrease in ISG15 expression in severe COVID-19 patients, we cannot tell if the change causes severity or is in response to it." (PMID 38580667, 2024). "The innate immune response, toll-like receptor pathways, and the ISG15 pathway are implicated in the lung tissue’s antiviral response to COVID-19." (PMID 38932146, 2024). "As with similar viruses, SARS-CoV-2, the virus causing COVID-19, hijacks these pathways by removing ubiquitin and/or ISG15 from proteins using a protease called PLpro, but also by interacting with enzymes involved in ubiquitin/ISG15 machinery." (PMID 35204803, 2022). "H1N1, H3N2 (OK/483), or H5N1 co-infection with SARS-CoV-2 elevated the expression of IFN-β, IFN-λ1, IFN-λ2/3, and ISG15, which has been shown to be associated with pathology in severe COVID-19 and pro-inflammatory cytokines and chemokines upon H5N1 co-infection." (PMID 40431161, 2025). "However, Innate immune signatures such as MX1, USP18, and ISG15 in the NP were associated with Ct value at admission of COVID-19 patients." (PMID 39172244, 2024). "In addition, ISG15 expression exacerbates the inflammatory response of COVID-19, partially indicating the tissue damage caused by SARS-CoV-2 infection." (PMID 37007947, 2023). "Based on our data and previous research, we consider overexpression of ISG15 to be a key event in determining a positive outcome of severe COVID-19 and believe it to be a valuable target for therapeutic intervention." (PMID 40374692, 2025). "The free, extracellular ISG15 has been proposed to implicate in the hyperinflammation seen in severe COVID-19." (PMID 40218394, 2025). "In the acute hyperinflammatory phase, distinct subsets of monocyte-like cells (CD163+SLC39A8+CALR+ infMonos) and Tinf cells (MX1+IRF1+ISG15+) emerged, a phenomenon also observed in patients with sepsis and COVID-19." (PMID 40251340, 2025). "In severe COVID-19 cases (both SevereA and SevereD), NK cells exhibit significantly higher expression levels of IFNγ, while interferon-stimulated gene 15 (ISG15), and Myxovirus resistance protein 1 (MX1) were highly expressed in moderate cases." (PMID 39928675, 2025). "In COVID-19, the lung tissue response to the viral invasion becomes evident when evaluating the ISG15 pathway." (PMID 38932146, 2024). "Despite similar inflammatory responses elicited in both chorion and amnion, upregulated DEGs exclusively found in COVID-19 maternal-chorion were enriched for antiviral ISG-15, MDA-5, RIG-I, and interferon pathways." (PMID 39390219, 2024). "While the ISG15 pathway’s role in antiviral response is established, it is emerging as a key facilitator of local inflammation and poor outcomes in COVID-19." (PMID 38932146, 2024). "When analyzed further, COVID-19 acute necrotizing encephalopathy patients also had various ISGs upregulated (e.g., ISG15, IF27 and IFITM1/2/3 etc.), consistent with our GO analysis." (PMID 37848421, 2023). "Following SARS-CoV-2 infection, a study found that the secretion of ISG15 exacerbated the inflammatory response, indicating the immunological role of ISG15 in COVID-19." (PMID 37007947, 2023). "In hospitalized COVID-19 patients, ISG15 is among the strongest up-regulated genes in immune cells as well as in respiratory epithelial cells and appears to be an important orchestrator of inflammation." (PMID 37614228, 2023). "Plasma concentrations of secreted ISG15, which were elevated in COVID-19 patients as compared to healthy volunteers, were significantly inhibited by dexamethasone." (PMID 37614228, 2023).